IGF1 (insulin like growth factor 1)
Diseases named in the same sentence as IGF1 in open-access papers (continued):
Sharing a sentence is not in itself a finding about the gene and the disease.
breast cancer (continued). "Furthermore, activation of IGF-1 signaling in breast cancer and neuronal cells protects from EnR-stress-induced apoptosis by enhancing EnR stress responses to promote cellular adaptability for cell survival maintenance." (PMID 30458886, 2018). "These conditions are associated with hyperglycemia and increased insulin and insulin-like growth factor 1 (IGF1) levels that may contribute to breast cancer initiation, progression and resistance to treatment." (PMID 30524378, 2018). "MiR-17-5p also abrogated the insulin-like growth factor 1-mediated growth of breast cancer cells." (PMID 29351283, 2018). "Diet has been cited as an important consideration when seeking to promote improved health among breast cancer survivors given the dietary effects which can be present on hormones related to breast cancer development/metastasis such as estrogen, insulin, and IGF-1." (PMID 29880779, 2018). "Women giving birth to heavier offspring tend to have higher oestrogen and free oestrogen levels and insulin-like growth factor 1 (IGF1) levels in pregnancy, giving a plausible mechanism for an association of high birthweight of offspring with maternal breast cancer risk." (PMID 30286782, 2018). "In addition, laboratory studies have shown that IGF-1 can regulate the growth and increase the proliferation of breast cancer cells (MCF-7) grown in vitro and decrease the death of mammary tumor cells in laboratory animals." (PMID 28865460, 2017). "High concentrations of IGF-1 in plasma are positively correlated with breast cancer." (PMID 28977849, 2017). "We analyzed gene expression data from published studies representing almost 5000 breast cancer patients to investigate whether GPER and IGF1 signaling establish an angiocrine gene signature in breast cancer patients." (PMID 29212519, 2017). "CLA’s have significant impacts on cell proliferation and differentiation, as evidenced by their effects on mammary ductal elongation and terminal end-bud formation (mediated via IGF-1;), and its suppression of chemical carcinogen-induced mammary tumor burden in rats." (PMID 28125600, 2017). "Overall, our study provides novel evidence regarding the angiocrine action elicited by IGF1 in breast cancer through the activation of HIF-1α/VEGF signaling pathway, emphasizing the important role played by GPER in the modulation of this relevant transduction axis." (PMID 29212519, 2017). "A range of signaling mechanisms, including IL-6, IGF-1, leptin, and adiponectin, have been proposed to explain how mature adipocytes alter breast cancer cell behavior, but the role of adipocyte-derived fatty acids as direct metabolic substrates has not been investigated." (PMID 28101337, 2017). "The growth-promoting effects of IGF-1 are mediated primarily through IGF1R, and high cytoplasmic expression of IGF1R in terminal duct lobular units (TDLUs) has been associated with significantly increased risk of later-life breast cancer." (PMID 28822014, 2017). "Overall, CPT is a natural anti‐oestrogen agent and could inhibit ERα‐mediated IGF‐1/AKT/mTOR pathway to increase the sensitivity of the ERα‐positive resistant breast cancer cells." (PMID 28272775, 2017). "This supports the concept of a paracrine role of IGF‐1 in breast cancer." (PMID 27734632, 2016). "Findings to date on the role of IGF‐1 in breast cancer development vary depending on the study." (PMID 27734632, 2016). "Additionally, gene set enrichment analysis of the spatio-temporal gene set with a gene set of 24 mouse models for breast cancer led us to identify a potential new function for insulin-like growth factor 1 (Igf1r) in the basal epithelium during lactogenesis." (PMID 27808166, 2016). "IGF-1 was less potent in EFM-19 than in MCF-7 but in both cells lines the protective effect of IGF-1 was maximal at a concentration of 15 ng/ml which indicates that the protective effect of IGF-1 in oestrogen-responsive breast cancer cells is mediated by the type I IGF receptor." (PMID 26801096, 2016).
breast cancer (continued). "The downstream signal transduction pathways that might be responsible for the protective effect of IGF-1 in oestrogen-responsive breast cancer cells were investigated." (PMID 26801096, 2016). "In contrast, C3G/Rap1 pathway mediates IGF-1-induced migration of MCF-7 breast cancer cells." (PMID 27286263, 2016). "Evidence from in vitro studies indicates that genistein, a main component of soy isoflavones, may stimulate the IGF-1 signaling pathway in human breast cancer cells at pharmacological doses." (PMID 27631779, 2016). "Likewise, NDRG2-overexpressing breast cancer cells exhibited a reduced level of p-Akt even after stimulation with IGF-1 (Insulin-like growth factor 1)." (PMID 27447861, 2016). "Although increased IGF1 plasma levels were positively associated with poor prognosis of different kinds of cancer including breast cancer 34, 35, the mechanism is still not clear." (PMID 26923183, 2016). "Next, we evaluated whether CCL5 and IGF-1 could be detected in peritumoral adipose tissue of women with breast cancer." (PMID 27027351, 2016). "IPA set in context a number of gene expression changes among which pathways involving PI3K, MEKK and IGF-1 may be of particular relevance in the setting of breast cancer." (PMID 27658825, 2016). "Our findings suggested that targeting EphA4 may lead to a novel inhibiting effect combined with other regulators in breast cancer therapy, especially where the tumor cell proliferation and survival are dependent on local tissue IGF1 production." (PMID 26923183, 2016). "For all-cause and breast cancer-specific mortality, no heterogeneity of effects was observed by race/ethnicity for IGF1 (P for interaction 0.26 and 0.45, respectively), IGF1R (P for interaction 0.43 and 0.72), or IGFBP2 (P for interaction 0.49 and 0.32)." (PMID 25619494, 2015). "Mifepristone inhibits growth induced by EGF in vitro and it may block the activation of IGF-1 signaling in some breast cancer cell lines." (PMID 26146614, 2015). "Therefore, we report that AGR2 is a key modulator involved in IGF-1-induced breast cancer development." (PMID 25956506, 2015). "IL-6 signaling pathways occur early in the inflammatory cascade with subsequent downstream effects on insulin-signaling molecules and insulin pathways (e.g., IGF-1), which may be related to weight gain, recurrence, and survival of patient with breast cancer." (PMID 25793000, 2015). "However, the specific modulator related to IGF-1-induced breast cancer development is still poorly understood." (PMID 25956506, 2015). "For example, in a hospital-based case-control study of 74 female breast cancer patients and 76 controls, HMW was shown to be strongly and inversely associated with breast cancer risk, independent of classical risk factors such as leptin and the IGF-1 system." (PMID 26070203, 2015). "We examined the expression profiles of the IGF1, IGF1R, IGFBP2 (IGF-binding proteins), and IGFBP3 proteins in breast tumor tissue and their relationships with all-cause and breast cancer-specific survival up to 17 years postdiagnosis in a multiethnic series of 358 patients in Hawaii, USA." (PMID 25619494, 2015). "Thus, mTORC1 is an important upregulator of telomerase in breast cancer, which contributes to the carcinogenic effects of increased IGF-1/mTORC1 signaling." (PMID 26225961, 2015). "Physiologically, patients with high IGF-1 circulatory levels have been shown to have reduced survival from breast cancer; hence, the upregulation of Cyr61 which mediates cell migration may result in increased metastasis observed." (PMID 25062088, 2014). "Ligands that bind to ErbB receptors were the most broadly active (every tested ErbB ligand elicited a significant response in at least 35 lines), followed by FGF-1/2, HGF, and IGF-1/2, consistent with the known importance of these ligands in breast cancer biology." (PMID 24655548, 2014).
breast cancer (continued). "While the interplay between the IGF and estrogen signaling pathways was initially dissected in breast cancer models, further studies investigated the impact of estrogens on IGF1 action in additional steroid hormone-dependent cancers, including endometrial tumors." (PMID 24904527, 2014). "In the present study, we examined the main effects of dietary intake and genetic polymorphisms on circulating IGF-1 and IGFBP-3 concentrations among women aged 40 years or older, a population with high breast cancer incidence in China (more than 42.3 per 100,000)." (PMID 25285521, 2014). "These growth factors include insulin-like growth factor-I (IGF1), which is found to act through a complex cross-talk with estrogen to stimulate the proliferation of normal mammary epithelium to increase the risk of breast cancer." (PMID 25034939, 2014). "Notably, knock-down of APP in metastatic breast cancer cells limited cell migration and invasion ability upon stimulation of IGF-1." (PMID 25491510, 2014). "Additionally, knockdown of Gi2α slightly reduced EGF-, bFGF-, or IGF-1-induced breast cancer invasion." (PMID 24521094, 2014). "Consistently, in our experimental conditions addition of 10 nM OHPg reduced the cellular content of pAKT and total AKT and its downstream target mTOR either in basal conditions or following treatment with IGF-1, a relevant factor in breast cancer growth and progression." (PMID 25216078, 2014). "Nevertheless, the IGF1 and EGF are stimuli to migration of cancer cells to distant areas, to form metastasis, and have been implicated in the development and progression of human breast carcinoma." (PMID 24591761, 2014). "Among them IL-6, TGF-β and IGF-1 might contribute to the development of brain metastasis in breast cancer cells." (PMID 24324647, 2013). "The metabolic alterations associated with obesity, including changes in insulin and insulin-like growth factor binding protein 1 (IGFBP-1) serum levels (which result in increased circulating free IGF-1 levels), are also significantly correlated with breast cancer recurrence and mortality." (PMID 23880059, 2013). "Aberrant activation of leptin and IGF1 signaling pathways has been shown to result in increased cell proliferation, enhanced epithelial to mesenchymal transition, and greater invasiveness of breast cancer." (PMID 24260287, 2013). "The hypothesis that breast cancer may start in utero is supported by studies indicating that the number of mammary stem cells is increased by in utero exposure to estrogen and IGF-1." (PMID 34589269, 2013). "In breast cancer, local IGF-1 production is mediated by surrounding stromal cells." (PMID 22852056, 2012). "Importantly, small-molecule inhibitors of MEK1 circumvented the prosurvival action of IGF-1 by restoring Bim to levels that more effectively mediated apoptosis in ER+ breast cancer cells." (PMID 22429491, 2012). "However, tumor weights from mice receiving the 30% CR + IGF-1 regimen were not statistically different from either CR or control mice, suggesting the IGF-1 infusion partially rescued the reduced mammary tumor growth observed in CR mice." (PMID 23342276, 2012). "Elevated levels of IGF-1 are also found in human breast cancer patients." (PMID 23320178, 2012). "Other proposed mechanisms include (i) a joint effect of insulin-like growth factor 1(IGF-1) and estrogens on breast cancer risk; (ii) a potential link between loss of genetic imprinting of IGF-2, which could play a role in fetal growth and breast cancer risk." (PMID 23061041, 2012). "We previously reported that STAT5b may mediate the transcriptional activation of IGF-1 and cyclin D1 after hypoxic stimulation in human breast cancer cells." (PMID 22485142, 2012). "This study has identified the IGF-1/IGF-IR/MEK prosurvival axis that exists in ER+ breast cancer cells to attenuate significantly the cytotoxic action of antiestrogen and antiprogestin treatment, with little effect on the antiproliferative action of these hormones." (PMID 22429491, 2012).
breast cancer (continued). "Here we have defined, for the first time, specific miRNAs under the direct regulation of IGF-1 signaling in the estrogen receptor positive MCF-7 breast cancer cell line and demonstrate kinase signaling as a modulator of expression for a small subset of microRNAs." (PMID 23226206, 2012). "Furthermore, reduced IGF-1 levels can account, at least in part, for many of the effects of CR on gene expression and mammary tumor burden." (PMID 23342276, 2012). "Circulating levels of IGF-1- and IGF-binding proteins have been found to be associated with several types of cancers, including colon, prostate, and breast cancer." (PMID 22315049, 2012). "Therefore, we performed a miRNA microarray to determine the effects of IGF-1 treatment on miRNA expression in the ER+ MCF-7 breast carcinoma cell line." (PMID 23226206, 2012). "IGF1 promotes cell motility in human breast carcinoma cell lines that predominately express IRS2." (PMID 23112878, 2012). "In addition, although both IGF-1 levels and TGF-β signaling are associated with the metastatic potential of breast cancer, the mechanism of TGF-β activation and its effect on cell invasion is still poorly understood." (PMID 21535875, 2011). "Finally, we have identified a first negative regulator of PAX2 activity in luminal breast cancer cells, IGF-1." (PMID 22168360, 2011). "The inhibition of anti-invasive factors such as PAX2 may contribute to the pro-invasive and pro-metastatic effects of IGF-1 in breast cancer cells." (PMID 22168360, 2011). "Circulating IGF-1 levels are higher in breast cancer patients compared with normal controls." (PMID 21535875, 2011). "Insulin-like growth factor 1 receptor (IGF-1R), which shares approximately 60% homology with IR, is a transmembrane tyrosine kinase activated by the binding of its ligand (IGF-1) and promotes mitogenic, metastatic, and anti-apoptotic phenotypes in breast cancer." (PMID 22203527, 2011). "Hormonal factors influencing the natural history of breast cancer (e.g., insulin, IGF-1, estradiol) could have effects in very short amounts of time." (PMID 22203527, 2011). "The levels of IGF1 and IGFBP3 combined may be associated with breast cancer by stimulating proliferation of breast epithelial cells." (PMID 20302654, 2010). "For the other factors there was no significant heterogeneity in the association of IGF1 with breast-cancer risk." (PMID 20472501, 2010). "The relationship of IGF1 (and IGFBP3) with breast-cancer risk factors is also unclear." (PMID 20472501, 2010). "Insulin-like growth factor 1 (IGF1) promotes breast cancer and disease progression." (PMID 19536088, 2009). "Mammographic density, a strong risk factor for breast cancer, has been positively associated with the ratio of IGF1 to insulin-like growth factor binding protein (IGFBP)-3 in premenopausal women, and has been shown to modify the breast cancer risks in BRCA1 and BRCA2 mutation carriers." (PMID 19843326, 2009). "We then examined the effect of IGF1 blockade on growth of 4T1.2 mammary tumours in vivo." (PMID 19536088, 2009). "Most breast cancer specimens show both IGF1 and insulin receptors." (PMID 22493645, 2009). "It is still unclear why increased serum IGF-1 level may have a sheltery effect on the risk of cervical cancer, whereas the unfavourable effect of serum IGF-1 is addressed in certain sex hormone-related cancers, such as prostate cancer or breast cancer." (PMID 18781172, 2008). "To comprehensively examine the role of common genetic variation in the IGF1, IGFBP1, and IGFBP3 genes in relation to circulating IGF-I and IGFBP-3 levels and breast cancer risk, we conducted a haplotype-based analysis in the NCI Breast and Prostate Cancer Cohort Consortium (BPC3)." (PMID 18596909, 2008). "In a systemic review, high serum IGF-1 levels were associated with increased risk of prostate and premenopausal breast cancer, but not with increased risk of lung cancer or colorectal cancer." (PMID 18781172, 2008).
breast cancer (continued). "These new mechanistic insights may also aid in understanding the role of SirT1 in breast cancer as well as in other organs in which local IGF-1 plays an important role." (PMID 17201918, 2007). "As early-onset breast cancer in itself is associated with a poorer prognosis, it may be advantageous to initiate breast cancer screening among multiparous women with the IGF1-19/-19 genotype at an earlier age." (PMID 17311016, 2007). "In women who never had used OCs, the IGF1-19/-19 genotype was associated with a decreased risk of early-onset breast cancer as compared with women who have at least one copy of the 19-repeat allele (IGF1+19)." (PMID 17311016, 2007). "If confirmed, IGF1-19/-19 may help identify a subgroup of women for earlier breast cancer screening." (PMID 17311016, 2007). "If confirmed, the IGF1-19/-19 genotype may help identify a subgroup of patients for whom early breast cancer screening is warranted as well as a subgroup of patients for whom the onset of regular screening can safely be postponed." (PMID 17311016, 2007). "The one uniparous patient with the IGF1-19/-19 genotype whose breast cancer was diagnosed before age 50 years had in fact had several recognised pregnancies; no patient with the IGF1-19/-19 genotype with less than two recognised pregnancies was diagnosed before age 57 years." (PMID 17311016, 2007). "Breast cancer risk appears to be influenced by the interaction between the IGF1 genotype and non-genetic factors." (PMID 17311016, 2007). "Given the absence of previous functional or epidemiologic data on the IGF1 SNPs we found associated with breast cancer risk, we calculated FPRPs by using a prior probability of true association." (PMID 16404426, 2006). "In the general population, high IGF-1 levels have been linked to premenopausal, but not to postmenopausal, breast cancer (Jernström and Barrett-Connor, 1999)." (PMID 15756256, 2005). "The aims of this study were to elucidate the relationships between IGF1 genotype, early-onset breast cancer, breast volume, circulating IGF-1 levels, pregnancy and OC use in a prospective cohort of healthy premenopausal women from high-risk breast cancer families." (PMID 15756256, 2005). "Absence of the IGF1 19-repeat allele was associated with breast cancer during follow-up (log-rank P=0.002)." (PMID 15756256, 2005). "Our preliminary analyses suggest an increased risk of early-onset breast cancer risk after hormonal exposure, such as teenage hormonal contraception or a pregnancy, in women lacking the IGF1 19-repeat allele." (PMID 15756256, 2005). "Our results suggest that lack of the IGF1 19-repeat allele modifies IGF-1 levels, breast volume and possibly early-onset breast cancer risk after hormone exposure in young high-risk women." (PMID 15756256, 2005). "It has been reported that IGF-1 upregulates MMP-9 in breast cancer cells." (PMID 14997210, 2004). "Furthermore, we investigated the relation between race/ethnicity, mean plasma IGF1 levels and breast cancer rates in the Hawaii/Los Angeles Multiethnic Cohort." (PMID 12610514, 2003). "Several studies have suggested that elevated circulating IGF-1 confers negative prognostic significance, both in unselected breast cancer populations and in women undergoing endocrine therapy, where IGF-1 activation has been linked to therapeutic resistance and disease progression." (PMID 41157306, 2025). "However, studies of premenopausal women show that the risk of breast cancer is associated with high IGF-1 concentration, and the amount of consumed lycopene reduces the concentration of IGF-1 circulating in the blood by stimulating the synthesis of the IGF-1 binding protein." (PMID 41515350, 2025). "Our findings also showed that the C allele of IGFBP-3 A-202C (SNP rs2854744) correlated with higher circulating IGF-1 levels (rs = 0.175, p ≤ 0.001), which were associated with an elevated likelihood of breast cancer (OR= 1.010; 95%CI, 1.006–1.015) (data not shown)." (PMID 40493660, 2025).